GDF15 (growth differentiation factor 15)
Diseases named in the same sentence as GDF15 in open-access papers (continued):
Sharing a sentence is not in itself a finding about the gene and the disease.
COVID-19 (continued). "Only a few studies have reported higher GDF-15 levels in COVID-19 patients than in healthy people." (PMID 34829345, 2021). "Additionally, we measured GDF-15, which displayed considerably higher levels in all COVID-19 patients." (PMID 33123167, 2020). "We refrained from a statistical comparison between HC and COVID-19 patients with regard to GDF-15." (PMID 33123167, 2020). "Since GDF15 was measured as part of the proteomics panel in the UKB, we assessed whether it mediated positive associations between pro-inflammatory cytokines and hospitalization or death from COVID-19." (PMID 41280118, 2025). "GDF15, which is produced in response to metabolic stress and has been found to induce immune tolerance in response to chronic inflammation, mediated 28% of the TNFR1-related COVID-19 health risk, as well as 38% of the age-related increased risk independent of TNFR1." (PMID 41280118, 2025). "GDF15 plays a role in immune suppression or tolerance in response to chronic inflammation, which could increase vulnerability to novel viral infections like COVID-19." (PMID 41280118, 2025). "In the present study, we aimed to quantify the circulating levels of novel serum biomarkers including GDF-15, PIVKA-II, sdLDL, suPAR, and of CRP in hospitalized COVID-19 patients compared with healthy subjects and to evaluate their association(s) with outcomes in COVID-19." (PMID 38700782, 2024). "However, there is no causal relationship between GDF-15 and hospitalization or susceptibility to COVID-19." (PMID 37773870, 2023). "Therefore, these verdicts suggest that the increasing levels of GDF15 might be due to the development of mitochondrial stress and dysfunction in severely affected COVID-19 patients." (PMID 36140453, 2022). "Therefore, higher expression of GDF15 in COVID-19 might a compensatory mechanism to stabilize and counteract dysregulated inflammatory reactions." (PMID 36140453, 2022). "Therefore, the higher expression of GDF15 in COVID-19 might a compensatory mechanism to stabilize and counteract dysregulated inflammatory reactions through the inhibition of inflammatory signaling pathways and augmentation of anti-inflammatory pathways." (PMID 36140453, 2022). "Therefore, the elevation of GDF15 in critical COVID-19 patients mirrors immunothrombotic events." (PMID 36140453, 2022). "Furthermore, the potential outcome of treating early COVID-19 patients with recombinant GDF-15 could be explored in further studies." (PMID 35251002, 2022). "Thus, higher serum levels of GDF15 in severely affected COVID-19 patients mirror hypoxic state." (PMID 36140453, 2022). "The mechanism of high GDF-15 levels in COVID-19 remain unknown." (PMID 35095877, 2021). "Besides the higher CRP and lower lymphocyte count levels, GDF-15 concentrations were higher in patients with moderate to severe COVID-19 during acute infection as compared to those with mild COVID-19 and controls, and GDF-15 concentrations remained elevated at follow-up." (PMID 34333238, 2021). "In COVID-19 positive patients, as COVID-19 severity worsened from mild to fatal, the plasma GDF-15 levels increased with the highest median GDF-15 levels detected in the fatal group (p<0.0001)." (PMID 38686386, 2024). "We found a positive correlation between GDF-15 and TGF-β1 levels, with an inverse correlation between GDF-15 and IL-10 in COVID-19 patients." (PMID 38686386, 2024). "Therefore, GDF15 may be used as an index to evaluate disease severity in patients with COVID-19." (PMID 37093513, 2024). "We thus concluded that WFDC2, GDF15, CHI3L1, and KRT19 were four key proteins related to COVID-19 severity." (PMID 36331721, 2023). "The common plasma proteins that were higher in the COVID-19 patients than controls and that were higher in the late recovery group than the early recovery group for phases 1 and 2 were WFDC2, CHI3L1, GDF15, KRT19, and TNFRSF10B." (PMID 36331721, 2023).
COVID-19 (continued). "Compared to other inflammatory markers including CRP, ferritin, and D-dimer, GDF-15 was more sensitive and specific in diagnosing the early stage of COVID-19 severity and admission to the ICU in seriously afflicted COVID-19 patients." (PMID 37974205, 2023). "In COVID-19 patients with severe clinical grading, those who were hospitalized in the PICU, and those who died, serum GDF-15 levels were greater." (PMID 37974205, 2023). "The COVID-19 patients who were admitted to the PICU, with severe clinical grading and those who died had significantly higher GDF-15 than those admitted to the ward, having mild to moderate grading, and those who survived." (PMID 37974205, 2023). "Plasma analysis confirmed distinct fibrosis biomarkers (TSP2, GDF15, IGFBP7, Pro-C3) that predicted the fatal trajectory in COVID-19." (PMID 36206625, 2022). "GDF15 is a known marker of mitochondrial dysfunction, and due to its function as hormone-cytokine may play an important role in the regulation of cellular oxygenation and the inflammatory response, all of which are key mechanisms in the pathophysiology of COVID-19." (PMID 35937703, 2022). "Our results show that while circulating GDF15 and ACE2 stratify COVID-19 patients according to disease severity, ACE2 missense SNPs constitute a risk factor linked to infection susceptibility." (PMID 35937703, 2022). "A prospective study involved 135 COVID-19 patients, 35 (28%) of them were admitted to ICU and 97 (79%) had higher GDF15 baseline level." (PMID 36140453, 2022). "In severely affected COVID-19 patients with ARDS at ICU, the anti-inflammatory IL-10 and GDF15 were increased, positively and negatively correlated with pro-inflammatory IL-6 and lymphopenia, respectively." (PMID 36140453, 2022). "GDF15 in severely affected COVID-19 patients is more specific than IL-6, CRP, ferritin and D-dimer in detecting the early stage of COVID-19 severity and admission to the intensive care unit (ICU)." (PMID 36140453, 2022). "In the present study, we measured the levels of circulating GDF15 and ACE2 in plasma of patients with COVID-19 who were admitted to the ICU and died and admitted to the ICU who recovered, as well as in an uninfected matched control group." (PMID 35937703, 2022). "Furthermore, GDF15 serum level may predict COVID-19 severity and mortality." (PMID 36140453, 2022). "Therefore, GDF15 might serve as an indicator of disease severity in COVID-19 patients." (PMID 34335566, 2021). "However, the top upregulated gene was Growth and differentiation factor 15 (GDF15) (a member of the TGF-β superfamily), which in COVID-19, increases with tissue damage." (PMID 41472300, 2025). "Using the Biobanque Québécoise de la COVID-19 (BQC19) and plasma proteomics analysis, we quantified GDF-15 and other markers of interest for a total of 1211 participants, representing both COVID-19 positive cases and non-COVID-19 hospitalized controls." (PMID 38686386, 2024). "Although higher levels of GDF-15 were noticed in obese (body mass index greater than 30) patients with COVID-19, this difference was not significant (p = 0.24)." (PMID 38686386, 2024). "Longitudinal assessment of 7 pairs of acute COVID-19 patients showed no trend in variations in plasma GDF-15 levels after 30 days follow up." (PMID 38686386, 2024). "Our findings align with the majority of studies conducted so far, indicating a higher expression of GDF-15 at the moment of hospitalization in patients with a negative outcome of COVID-19." (PMID 38672113, 2024). "Compared to hospitalized controls, COVID-19 infected patients exhibited higher average plasma GDF-15 levels regardless of presence or absence of comorbidities." (PMID 38686386, 2024). "As age remains an important risk factor for severe COVID-19 and GDF-15 increases with age, our multivariable analysis indicated significantly elevated GDF-15 levels irrespective of the specific type of comorbidity in COVID-19 patients." (PMID 38686386, 2024).
COVID-19 (continued). "In this study, despite the small sample size and non-performance of multivariate analysis, GDF15 showed good discrimination capacity, proposing a potential biomarker in evaluating prognosis in patients with COVID-19." (PMID 37408184, 2023). "In the present study, GDF15, WFDC2, and CHI3LI were correlated with age in the COVID-19 patients." (PMID 36331721, 2023). "The first study to investigate GDF-15 in COVID-19 was a hypothesis-generating case series of 66 patients, which showed an increase in GDF-15 in COVID-19 cases with a fatal outcome." (PMID 35326373, 2022). "In the present study, we measured the levels of circulating growth differentiation factor 15 (GDF15) and angiotensin-converting enzyme 2 (ACE2) in plasma of severity-stratified COVID-19 patients and uninfected control patients and characterized the in vitro effects and cohort frequency of ACE2 SNPs." (PMID 35937703, 2022). "Pooled analysis demonstrated that the GDF15 serum was significantly correlated with most of COVID-19 regardless of its severity." (PMID 36140453, 2022). "More studies are needed to elucidate the role of GDF15 and ACE2 in COVID-19." (PMID 35937703, 2022). "Our findings, together with those from other studies suggest that GDF-15 is increased in patients with severe COVID-19, but not in asymptomatic or mild infections." (PMID 36163447, 2022). "We hypothesize that plasma markers (e.g. (TSP2, GDF15, IGFBP7, Pro-C3) could detect the of early fibrotic changes in COVID-19." (PMID 36206625, 2022). "In contrast, the GDF-15 levels were statistically greater among the subjects with severe COVID-19 compared to the asymptomatic and mild groups, but not in the comparison with the control group." (PMID 36163447, 2022). "The present perspective had several limitations including scarcity of clinical studies and serial measurement of the GDF15 in the initial and late phases of COVID-19 patients were not reported." (PMID 36140453, 2022). "Finally, a total of eleven differential factors related to COVID-19 disease severity were identified, including: TRAIL R1, IGFBP-1, IGFBP-4, VCAM-1, sFRP-3, FABP2, Transferrin, GDF15, IL-1F7 (also known as IL-37), IL-5Rα, and CD200." (PMID 34335566, 2021). "Although increased ferritin is a poor predictor of COVID-19 outcome, we could not prove its correlation with the GDF-15 level in our study." (PMID 37974205, 2023). "However, this review—unlike other studies which implicate GDF15 in the pathogenesis and severity of COVID-19,—confirmed that the increase in GDF15 in COVID-19 could be a compensatory mechanism against hyperinflammation and exaggerated immune response." (PMID 36140453, 2022). "Moreover, the negative correlation between GDF-15 and our logistic regression model suggests that serum catestatin could also be a predictor of a poor COVID-19 outcome." (PMID 35956112, 2022). "We found that plasma exosomes from COVID-19 patients significantly induced the production of the same set of cytokines and chemokines that contribute to the severity of COVID-1949–53, including IL-6, IL-8, TNF-α, IFNγ, CCL1, and GDF-15, in PBMCs compared with those from non-COVID donors." (PMID 36526691, 2022).
Sepsis (52 papers, 2017 to 2026). Sepsis is defined as life-threatening organ dysfunction caused by a dysregulated host response to infection. "Regarding the biomarkers we tested, GDF-15 and suPAR levels were associated with the development of infectious complications, including pulmonary and urinary, as well as sepsis." (PMID 38700782, 2024). "In vivo and in vitro models of sepsis were applied to elucidate the role and mechanisms of GDF15 in sepsis-associated lung injury." (PMID 38725041, 2024). "Assessment of the diagnostic value of GDF-15 highlighted its role as a biomarker of sepsis severity, including septic shock." (PMID 39000420, 2024). "GDF15 deficiency aggravated renal and cardiac injury in sepsis due to increased inflammatory cytokines." (PMID 38725041, 2024). "Previous studies have demonstrated the association of GDF15 with the prognosis of septic patients as well as its controversial roles in sepsis-related tissue damage." (PMID 38725041, 2024). "In the present study and in a previous report, GDF-15 levels were associated with mortality in sepsis patients." (PMID 35095877, 2021). "GDF-15 level in severe sepsis was significantly associated with organ dysfunction markers such as creatinine (kidney) and bilirubin (liver), and disease severity markers such as lactate, hs-CRP, APACHE II score and SOFA score." (PMID 34441955, 2021). "Our study found that GDF15 will increase in sepsis caused by various pathogens, which is one aspect of GDF15 superior to PCT." (PMID 34566964, 2021). "Using Gdf15-deficient mice, we show that GDF15 plays a causal role in sepsis by delaying the local control of infection." (PMID 32424099, 2020). "To distinguish between these two possibilities, we compared the survival rates of WT and Gdf15-deficient (Gdf15−/−) mice in response to a polymicrobial peritonitis using the CLP model of sepsis." (PMID 32424099, 2020). "GDF-15 was further increased in sepsis and showed a strong association with organ dysfunction (kidney, liver and lactate) and disease severity (APACHE II and SOFA score)." (PMID 29180833, 2017). "For the large subgroup of sepsis patients, GDF-15 was an independent risk factor for an unfavorable long-term survival, too (HR 2.0; 95% CI 1.02–3.88)." (PMID 29180833, 2017). "Collectively, serum GDF-15 levels are significantly increased in critically ill patients, associated with sepsis, organ failure, and disease severity." (PMID 29180833, 2017). "Additionally, the potential role of GDF15 as a diagnostic and prognostic marker in critical clinical conditions, such as sepsis, which pose significant diagnostic and therapeutic challenges, remains under investigation." (PMID 40941711, 2025). "Serum GDF-15 levels are elevated significantly in critically ill patients, associated with sepsis, organ failure, and disease severity; furthermore, high GDF-15 levels at the time of admission to the intensive care unit (ICU) can predict short- and long-term mortality risk." (PMID 40809145, 2024). "However, the regulatory role and the underlying mechanisms of GDF15 in sepsis remain poorly defined." (PMID 38725041, 2024). "However, the detailed regulatory effect and underlying mechanisms of GDF15 on AMs in sepsis-induced lung injury remains unexclusive." (PMID 38725041, 2024). "ROC curve also indicates that GDF15 has good diagnostic value for sepsis; meanwhile, the dynamic monitoring of GDF15 levels is of high prognostic value for patients with sepsis, and we speculate that GDF15 may be a biomarker of sepsis." (PMID 34566964, 2021). "GDF15 has also been reported to enhance sympathetic activity, which might be related to weight loss, increased exergy expenditure (EE) or protection against sepsis through fatty acid oxidation or maintenance of hepatic triglyceride export." (PMID 41034527, 2025).
Sepsis (continued). "An increased expression of GDF15 has been closely associated with the microenvironments of immune tolerance, e.g., diverse tumors, pregnancy, infections and sepsis, and many age-related diseases, such as cardiovascular disorders as well as chronic kidney and lung diseases." (PMID 39643709, 2024). "This study identifies GDF15 as a central guardian of mitochondrial-immune homeostasis in sepsis, positioning it as both a robust severity biomarker and a promising therapeutic target for mitochondrial resuscitation." (PMID 41660626, 2026). "Immune cell-specific enrichment of GDF15 expression provides biological context for its elevation during acute sepsis." (PMID 41918885, 2026). "Among patients with sepsis, higher GDF-15 levels were consistently observed in those with greater disease severity, and increased levels of inflammatory biomarkers." (PMID 41918885, 2026). "Analysis of independent single-cell transcriptomic data demonstrated increased GDF15 expression in immune cells during acute sepsis, with relative enrichment observed primarily in plasma cells and monocytes." (PMID 41918885, 2026). "Clinical analysis of a sepsis patient cohort (n=119) confirmed a significant elevation of circulating GDF15, with its levels strongly correlating with disease severity scores." (PMID 41660626, 2026). "Its weak correlations with classical inflammatory markers further indicate that GDF15 represents a distinct biological process in sepsis pathophysiology." (PMID 40941711, 2025). "Second, the authors investigated GDF15-regulated triglycerides using an LPS model of sepsis, while we used a co-infection model with live bacteria." (PMID 39951524, 2025). "Several recent clinical studies have further highlighted the prognostic value of GDF15 in patients with sepsis." (PMID 40941711, 2025). "First, in our study, fluoxetine-treated mice exhibit elevated serum Troponin during sepsis, while mice with GDF15 are spared from this." (PMID 39951524, 2025). "This study provides preliminary data revealing the temporal pattern of GDF15 levels and its relationship with classical inflammatory biomarkers in patients with sepsis." (PMID 40941711, 2025). "Integrating WGCNA with three machine learning algorithms, we identified six diagnostic genes—PGM3, GDF15, GART, GFOD2, E2F2, and ATP1B2—associated with sepsis-induced ALI, which were validated in clinical samples by Western blotting." (PMID 41142807, 2025). "Median values of IL-6, IL-18, and GDF15 were significantly higher in the sepsis and septic shock groups, compared to the non-sepsis group." (PMID 40681771, 2025). "Growth differentiation factor 15 (GDF15) protects against sepsis-induced ALI by suppressing the HIF-1α/LDHA glycolytic axis in pulmonary ECs, thereby reducing cytokine production and leukocyte recruitment." (PMID 41488672, 2025). "Our study provided the first evidence that GDF15 interplay with glycolysis to ameliorate sepsis-induced inflammation in AMs." (PMID 38725041, 2024). "Our data showed that GDF15 effectively limited AM inflammation and lung injury by inhibiting glycolysis and classical inflammatory signaling in sepsis." (PMID 38725041, 2024). "Our findings reveal the beneficial role of GDF15 in AM inflammation during sepsis, providing a potential therapeutic strategy for treating sepsis-related lung injury." (PMID 38725041, 2024). "GDF15 has been shown to be necessary for surviving both bacterial and viral infections, as well as sepsis, since it was needed for hepatic sympathetic outflow and triglyceride availability control." (PMID 38762719, 2024). "In the mouse model of lipopolysaccharide-induced sepsis, recombinant GDF15 inhibited the proinflammatory responses and alleviated lung tissue injury." (PMID 38725041, 2024). "Our study analyzed the levels of GDF15 and its correlations with the clinical prognosis of patients with sepsis." (PMID 38725041, 2024).